NLRP3 (NLR family pyrin domain containing 3)
Diseases named in the same sentence as NLRP3 in open-access papers (continued):
Sharing a sentence is not in itself a finding about the gene and the disease.
Obesity (continued). "Upregulation of the nucleotide-binding domain and leucine-rich repeat-containing proteins (NLRP3) inflammasome has been identified as a trigger of neutrophilic inflammatory response in patients with obesity-related asthma; it has been associated with a systemic inflammatory response." (PMID 37189844, 2023). "NLRP3 is negatively associated with obesity due to increased inflammation in adipose tissue." (PMID 37252693, 2023). "Furthermore, activation of the NLRP3 inflammasome is associated with insulin resistance and related diseases, including Alzheimer’s disease, obesity, and cardiovascular disease." (PMID 37367672, 2023). "Based on the role of NLRP3 in obesity-related metabolic syndrome, experiments have shown that saturated fatty acids activate the NLRP3 inflammasome by inducing the destruction of NKA caused by the accumulation of saturated phosphatidylcholine and the loss of plasma membrane fluidity." (PMID 36378463, 2023). "In addition, obesity is associated with activation of the Nod-like receptor family pyrin domain containing 3 (NLRP3) inflammasome, which can be manipulated in cardiomyocytes to produce an atrial substrate susceptible to AF." (PMID 35998035, 2022). "These mice were also protected from insulin resistance and metabolic dysfunction associated with obesity-induced DM, suggesting that NLRP3 inflammasome may act as a transducer to detect danger signals and trigger inflammatory responses in these diseases." (PMID 35844498, 2022). "Moreover, several other obesity-related inflammatory factors, including IL-17, leptin, adiponectin, NLRP3 inflammasome, and TLR-4 have been implicated in the pathogenesis of lung disease." (PMID 35360873, 2022). "NLRP3 deficiency attenuated obesity-related male infertility." (PMID 35915511, 2022). "NOD-like receptor protein 3 (NLRP3) is a well-characterized inflammasome responsible for inflammation and insulin-resistance development and is also associated with atrial fibrillation (another obesity-related comorbidity)." (PMID 36528638, 2022). "Of note, tranilast induced weight loss and exhibited antidiabetic properties in mice via NLRP3 inhibition, suggesting that this drug might reduce obesity-associated comorbidities." (PMID 35806353, 2022). "With the discovery that NLRP3 inflammasome mediates caspase-1 activation and IL-1β maturation, its relation with insulin resistance and type 2 diabetes development has been recognized; NLRP3 deficiency protects mice from obesity-induced insulin resistance." (PMID 36741414, 2022). "The NLRP3 inflammasome activates Caspase 1 and causes release of IL-1β, which in turn has been identified as the major driving force behind leukocytosis in obesity due to its stimulatory effect on myeloid stem cells, but also as contributing factor to the development of type 2 diabetes." (PMID 35931812, 2022). "As well, lipotoxicity induced by obesity has been associated with the production of ROS, which can lead to the activation of NLR family pyrin domain containing 3 (NLRP3), a potent stimulator of the inflammasome signaling whose primary effect is the production of IL-1β37." (PMID 34108550, 2021). "Importantly, NLRP3 expression in the adipose tissue has previously been associated with obesity-induced inflammation and insulin resistance in obese individuals, and diminishing NLRP3 levels can protect against insulin resistance in DIO mice." (PMID 33498469, 2021). "Moreover, obesity-associated DAMPs also activate multiprotein complexes through NLRs called inflammasomes, and the NLR family pyrin domain-containing 3 (NLRP3) inflammasome is the best characterized inflammasome." (PMID 34441565, 2021). "Importantly, obesity and insulin resistance (IR) have been associated with inflammation and subsequent activation of NLRP3 inflammasome." (PMID 34805147, 2021). "Obesity-associated PAMPs and DAMPs can activate the NLRP3 inflammasome." (PMID 35046893, 2021).
Obesity (continued). "Obesity-associated inflammation and NLRP3 inflammasome activation initially arise in WAT 43,44." (PMID 34646372, 2021). "So far, we have localized the NLRP3 inflammasome components within the isolated muscle fiber; this is a contribution to the initial understanding of chronic low-grade pro-inflammatory mechanisms associated with skeletal muscle tissue in an obesity context." (PMID 34638553, 2021). "Given that obesity might be associated with the development of aggressive clinical symptoms in COVID-19, we aimed to suggest the possible role of NLRP3 inflammasome as a link between obesity and the increased risk for a severe COVID-19 outcome." (PMID 33193349, 2020). "Another study found that obesity was associated with NLRP3 activation in adipose tissue." (PMID 33519369, 2020). "Cholesterol plays an important role in bile acid metabolism, and in the current study HFD-induced obesity was associated with a marked increase in total cholesterol, but importantly, this effect was significantly attenuated in obese NLRP3 deficient mice (P = 0.006)." (PMID 33273482, 2020). "Finally, the training protocol significantly inhibited the activation of the obesity-associated NLRP3 signaling pathway." (PMID 32624568, 2020). "Elevated NLRP3 signaling activity is associated with obesity and obesity-related chronic diseases." (PMID 32209983, 2020). "In addition, the underlying mechanism by which NLRP3 is activated in obesity and aging has recently be revealed." (PMID 32545355, 2020). "NLRP3 inflammasome activation may underlie obesity-induced inflammation and insulin resistance, and NLRP3 deficient mice exposed to high fat diet (HFD) appear to be protected from left ventricle (LV) concentric remodeling." (PMID 33273482, 2020). "In addition, NLRP6 and NLRP3 ablation has been associated with a worsening of multiple aspects of the metabolic syndrome, including obesity, via modulation of gut microbiota." (PMID 32751658, 2020). "Additionally, overexpression of NLRP3 inflammasome components in AT is associated with the pathogenesis of obesity and therefore is directly associated with T2D, atherosclerosis, and myocardial infarction." (PMID 32012695, 2020). "NLRP3 activation and associated inflammatory events may be especially important in conditions associated with increased aldosterone levels, such as obesity, metabolic syndrome, and arterial hypertension." (PMID 31817997, 2019). "Given that mitochondrial ROS are elevated in obesity, and ROS are implicated in NLRP3 inflammasome assembly, it is possible that mitochondrial dysfunction could influence NLRP3 inflammasome activation that results in pancreatic damage in obese patients." (PMID 31174550, 2019). "Importantly, NLRP3 activity has been linked to obesity and insulin resistance both in human and mouse studies." (PMID 31740673, 2019). "The findings suggest that voluntary running suppresses NLRP3 inflammasome activation and oxidative stress, and enhances NO production, and that these benefits have association with prevention of vascular dysfunction in obesity." (PMID 29932503, 2018). "However, the molecular pathways underlying the organ- and cell-specific activation of the NLRP3 inflammasome in the context of obesity have just stated to be elucidated." (PMID 30619282, 2018). "Moreover, it has been reported recently that the NOD-like receptor family pyrin domain containing-3 (NLRP3), one of the inflammasomes, is associated with obesity and contributes to obesity-induced inflammation." (PMID 29354072, 2017). "The major goal of this study was to determine whether endothelial hyperpermeability is associated with endothelial Nlrp3 inflammasome activation induced by increased level of saturated free fatty acid, an important danger signal associated with obesity." (PMID 27689324, 2016). "NLRP3 may be causally involved in the induction of obesity and insulin resistance, at least in mouse models." (PMID 27803798, 2016).
Obesity (continued). "MCP–1 (CCL2) in adipose tissue is reduced in NLRP3 deficient mice, suggesting that NLRP3 inflammasome plays a role in macrophage infiltration in adipose tissue and correlates with sustained levels of chronic inflammation in obesity." (PMID 26437377, 2015). "Obesity-induced pancreatic β-cell death is regulated, at least in part, by the NLRP3 inflammasome, as demonstrated in NLRP3-deficient mice in late-stage obesity, where the ablation of NLRP3 is associated with reduced cell death and increase in pancreatic islet size and local insulin levels." (PMID 23843683, 2013). "Indeed, mice deficient in NLRP3 are protected from high-fat-diet-induced obesity." (PMID 39496966, 2025). "Importantly, obesity has been associated with NLRP3 inflammasome activation." (PMID 38580672, 2024). "Furthermore, activation of the NLRP3 inflammasome has been shown to be associated with obesity-induced insulin resistance, which may indirectly influence the pathogenesis of OA and RA by aggravating systemic inflammation." (PMID 37474953, 2023). "Moreover, a positive association between the NLRP3 inflammasome and priming of murine ATMs toward a pro-inflammatory (M1) phenotype has been established, a process that contributes significantly to chronic low-grade inflammation in obesity." (PMID 37239938, 2023). "However, it is envisaged that NLRP3 inhibitors could be developed in the near future for use as effective therapeutics for obesity-associated metabolic and cardiovascular disorders." (PMID 37446154, 2023). "Researchers found that NLRP3-related inflammation was activated in the fat pads of leptin-deficient mice and high-fat diet-fed obese mice and that NLRP3-dependent caspase-1 activation in hypertrophic adipocytes may induce obesity and adipocyte death through pyroptosis." (PMID 35677632, 2022). "Nlrp3-deficient animals are protected from obesity-associated hepatic steatosis, adipose tissue inflammation, and glucose intolerance, supporting the notion that the effects of ceramides on NLRP3-dependent pathways may be relevant in the etiology of these metabolic disorders." (PMID 35789435, 2022). "Thus, age-induced (inflammaging) and obesity-induced NLRP3 hyperactivity could predispose patients to the cytokine storm often seen in severe COVID-19." (PMID 34564326, 2021). "Taken together, our results showed the presence and upregulation of NLRP3 inflammasome components in isolated muscle fibers during IR, supporting the idea of the skeletal muscle tissue as an active component of the inflammatory processes associated with obesity." (PMID 34638553, 2021). "However, basal levels of inflammation are low in this population, and it is unknown how raising β-OHB with exogenous ketone ingestion affects NLRP3 activation in individuals who are at risk for developing metabolic diseases (e.g., obesity)." (PMID 32209983, 2020). "Furthermore, activation of the Nlrp3 inflammasome in Wt C57BL/6 or Nlrp1b1-Tg bone marrow derived macrophages in response to ATP or danger signals associated with obesity like glucose or palmitic acid resulted in similar levels of IL-1β secreted to the culture supernatant." (PMID 31554824, 2019). "However, the exact mechanisms underlying the host’s sensing of obesity and hyperglycemia and how these danger signals trigger the NLRP3 inflammasome remain unclear." (PMID 31174550, 2019). "In addition, the obesity-induced dysbiosis of gut bacteria causes cholesterol metabolic disorders and the levels of bile acids are reduced in the gut, which impair the inhibition of NLRP3." (PMID 30050954, 2018). "In addition to NLRP3 functions in epithelial cells of the mucosal surface, the inflammasome is also related to the secretion of proinflammatory cytokines that contribute to obesity-associated chronic inflammatory conditions." (PMID 29104591, 2017). "However, the causal mechanisms underlying the activation of NLRP3 inflammasome during excess caloric consumption and obesity remain largely unknown." (PMID 28786950, 2017).
Obesity (continued). "We next investigated whether increased level of free fatty acid, a typical danger signal associated with obesity and type 2 diabetes, can elicit Nlrp3 inflammasomes in endothelial cells and subsequently contribute to the development of endothelial dysfunction and vascular injury." (PMID 27689324, 2016). "However, the pathological relevance of endothelial Nlrp3 inflammasome activation in obesity‐associated vasculopathy remains unclear." (PMID 26293846, 2015). "Several recent studies have shown that the NLRP3 inflammasome genes are associated with a number of autoimmune diseases including familial cold urticaria, Muckle-Wells syndrome and multiple inflammatory diseases such as Crohn's disease, obesity-induced inflammation and insulin resistance." (PMID 23110140, 2012). "Increased NLRP3 expression in both subcutaneous and visceral adipose tissues (SAT and VAT) has been positively linked to higher BMI and IR in individuals with obesity." (PMID 41596350, 2026). "The study highlights the significance of the NLRP3 inflammasome macrophages in the pathogenesis of adipose tissue inflammation in obesity." (PMID 41645554, 2026). "In obesity, NLRP3 activation within adipose tissue increases the production of pro-inflammatory cytokines, which can enter the circulation and contribute to CNS neuroinflammation, thereby exacerbating MS symptoms." (PMID 41562846, 2026). "In obesity, NLRP3 inflammasomes are activated by an excess of metabolic DAMPs such as ATP, glucose, FAs, ceramides, ox-LDL, crystallized uric acid, cholesterol crystals, and monosodium urate." (PMID 41562846, 2026). "Inhibiting NLRP3 activation has the potential to alleviate obesity-related complications, MS, and a range of other inflammatory diseases." (PMID 41562846, 2026). "NLRP3 inflammasome inhibition has been found to reduce obesity-related inflammation and improve insulin sensitivity." (PMID 41596350, 2026). "This study examined Rhein’s renoprotective effects in high-fat diet (HFD)-induced ORG mice and leptin-stimulated podocytes, focusing on P2X7R/NLRP3 inhibition to provide insights for obesity-related kidney diseases." (PMID 41586196, 2025). "The NLRP3 inflammasome as a sensor for metabolic danger signals that accumulate during obesity, thereby inducing the production of various cytokines and chemokines." (PMID 41169786, 2025). "GDVs preferentially enter microglia and inhibit brain inflammation through modulation of the NLRP3 inflammasome, which plays a key role in obesity-related neuroinflammation." (PMID 41560920, 2025). "The inhibition or genetic deletion of NLRP3 confers protection against diet-induced insulin resistance and obesity." (PMID 40648980, 2025). "In adipose tissue, obesity leads to adipocyte hypertrophy and recruitment of immune cells, particularly adipose tissue macrophages (ATMs), which are a major source of NLRP3 expression and inflammasome activity." (PMID 40943225, 2025). "IL-1β levels, determined by ELISA, were markedly higher in the obese group, confirming our recent report that obesity promotes atrial NLRP3 inflammasome activation." (PMID 39283528, 2025). "NLRP3 inflammasome is capable of sensing obesity-related danger signals and is closely related to insulin signals, glucose tolerance, and IR." (PMID 41264598, 2025). "Rhein’s binding to SIRT2 inhibits NLRP3 inflammasome activation in macrophages, promoting white adipose tissue thermogenesis during obesity." (PMID 41567643, 2025). "First, the domain‐like receptor protein 3 (NLRP3) inflammasome plays an important role in linking obesity to T3 inflammation." (PMID 40329860, 2025). "Retinol binding protein 4, the primary retinol carrier in serum, is elevated in individuals with obesity and type 2 diabetes and contributes to the priming of the NLRP3 inflammasome through TLR2 and TLR4." (PMID 40307577, 2025).
Obesity (continued). "In obesity mice, butyrate supplementation has been observed to suppress the expression of inflammatory factors such as IL-1β, NLRP3 and monocyte chemoattractant protein-1 in cardiac tissues." (PMID 40182777, 2025). "The nucleotide-binding domain and leucine-rich repeat family pyrin domain containing 3 (NLRP3) inflammasome plays a key role in the development of several complex inflammatory diseases, including obesity, Alzheimer’s disease and atherosclerosis." (PMID 41560920, 2025). "in 2014, heightened expression of NLRP3 inflammasome components was observed in damaged podocytes in a mouse model of obesity-induced glomerulopathy from a high-fat diet, indicating activation of the NLRP3 inflammasome." (PMID 40841164, 2025). "The NLRP3 inflammasome plays a pivotal role in modulating inflammatory responses within dysfunctional adipose tissue and is involved in obesity-related metabolic inflammation." (PMID 41372934, 2025). "Overall, these results support the link between obesity, NLRP3 inflammasome activation and reactive gliosis at the level of the intestinal mucosa." (PMID 39287080, 2025). "In the context of obesity, the NLRP3 was presented to act on cellular stress signals released from stressed or dying adipocytes in the form of danger-associated molecular patterns (DAMPs), which strongly activate the inflammasome." (PMID 41226484, 2025). "Overall, our results suggest that enteric glial NLRP3 inflammasome might represent an interesting molecular target for the development of novel pharmacological approaches aimed at managing the enteric inflammation and intestinal mucosal dysfunctions associated with obesity." (PMID 39287080, 2025). "We focused our attention mainly on the NLRP3 inflammasome pivotally involved in shaping immune/inflammatory responses in several disorders, including obesity." (PMID 39287080, 2025). "In contrast, inhibiting these cytokines reduced hyperresponsiveness and the NLRP3 inflammasome response in mouse models of obesity and asthma." (PMID 41007770, 2025). "The body weight-lowering effect of the inhibitors was compared with caloric restriction and the GLP-1 receptor agonist semaglutide, and NLRP3 inhibition reduced obesity to a similar extent." (PMID 39496966, 2025). "Promising implications arise from our study, which aims to elucidate the intricate involvement of the NLRP3 inflammasome pathway in the context of both obesity and COVID-19." (PMID 40004007, 2025). "Flavopiridol suppresses the activation of NLRP3 inflammasome induced by palmitate and improves obesity-related inflammation and insulin resistance through inducing macrophage autophagy." (PMID 40433411, 2025). "Accumulating evidence suggests that the NLRP3 inflammasome plays a central role in obesity‐induced insulin resistance." (PMID 41169786, 2025). "In summary, ALM attenuates inflammatory crosstalk between M1 macrophages and adipocytes by enhancing SIRT3-mediated mitophagy and suppressing NLRP3 inflammasome activation, thereby alleviating adipose tissue inflammation and pathological remodeling in obesity." (PMID 41372934, 2025). "Increasingly, the NLRP3 inflammasome is recognized as a critical molecular mediator at the intersection of obesity-induced inflammation and AF pathophysiology." (PMID 40649732, 2025). "Two different clinical-stage NLRP3 inhibitors, NT-0249 and NT-0796, have demonstrated that inhibiting NLRP3 reverses established diet-induced obesity in mice and provides metabolic benefits that extend beyond reversing obesity itself." (PMID 40104296, 2025). "Blautia wexlerae depletion in obesity disrupts acetate-mediated suppression of NLRP3, whereas its restoration attenuates pyroptosis and improves fertility." (PMID 40331931, 2025). "In conclusion, our study highlights the complexity of inflammatory responses in obesity and COVID-19, particularly related to NLRP3 inflammasome activation." (PMID 40004007, 2025).